NUCB1 (nucleobindin 1)
Diseases named in the same sentence as NUCB1 in open-access papers (continued):
Sharing a sentence is not in itself a finding about the gene and the disease.
tumor (8 papers, 2019 to 2023). "Intriguingly, we found that the mRNA levels of low-risk genes NUCB1 and GCAT were elevated in tumor tissues more than those in normal tissues, but they were lower in stage IV than in stages I–III." (PMID 37007952, 2023). "Tumor grafts formed from SW1990 cells overexpressing NUCB1 showed additive effects with GEM treatment, as indicated by decreased tumor volumes and decreased tumor weights." (PMID 33855021, 2021). "NUCB1 was expressed in almost all the samples tested (10/11, with low/intermediate intensity in the majority of tumor cells)." (PMID 33019700, 2020). "In our risk signature, we found that the low-risk genes NUCB1 and GCAT were higher in tumor tissues than in adjacent normal tissues in PRAD; however, their expression levels in the high stage were lower than those in the low stage and that the risk signature performed well in prognosis prediction." (PMID 37007952, 2023). "Notably, the differences between tumor and normal cells in NUCB1 mRNA expression were more pronounced than for IRF4 and ANXA5." (PMID 36611989, 2023). "The contribution of NUCB1 and ANXA5 in tumor progression and drug responses in DLBCL remains controversial, so revealing their exact roles in DLBCL behavior and prognosis needs further investigation." (PMID 36611989, 2023). "Our study reveals for the first time the function of NUCB1 in PDAC and suggests a tumor-suppressive role." (PMID 33855021, 2021). "Furthermore, overexpression of NUCB1 in SW1990 and CFPAC1 notably increased the anti-tumor effects of gemcitabine (GEM) compared to control vector, as indicated by increased apoptosis of NUCB1-overexpressing cells compared to control cells." (PMID 33855021, 2021). "Although NUCB1’s relevance in DLBCL has not previously been addressed, previous findings on other tumor cells revealed no consensus about NUCB1’s functions in tumor progression." (PMID 36611989, 2023).
neurodegenerative disease (2 papers, 2022 to 2024). A disorder of the central nervous system characterized by gradual and progressive loss of neural tissue and neurologic function. "According to the literature, NUCB1 protein is implicated in Alzheimer’s disease, other neurodegenerative diseases, or cellular processes known to be dysregulated early in tauopathy pathogenesis such as synaptic plasticity, proteostasis, glucose metabolism, and mitochondrial function." (PMID 36138887, 2022). "Recently, a paper indicated that an adult-viable mutant that completely disrupts the G protein α-subunit binding and activates NUCB1 plays a neuroprotective role in the Drosophila model of neurodegenerative disease." (PMID 36138887, 2022).
infection (1 paper, 2021). The state of being infected such as from the introduction of a foreign agent such as serum, vaccine, antigenic substance or organism. "Note that upregulation of CG10943 and Dif, and downregulation of CG8628, CG15096, NUCB1, and cbx in infected conditions have been previously associated with increased tolerance to infection." (PMID 34521452, 2021). "If we focus on particular genes, upregulation of CG10943 and Dif, and downregulation of CG8628, CG15096, NUCB1, and cbx in infected conditions has been associated with increased tolerance to infection." (PMID 34521452, 2021).
infectious disease (1 paper, 2023). A disorder directly resulting from the presence and activity of a microbial, viral, or parasitic agent in humans. "Malignant and reactive lymphocytes in NHL and infectious diseases contain more NUCB1 than resting lymphocytes." (PMID 36611989, 2023).
NUCB1 also shares sentences with these, for which no sentence is quoted: diabetes (2 papers); insulinoma (2); Parkinson disease (2); Autoimmunity (1); dementia with (1); familial amyloid polyneuropathy (1); Hypertension (1); leukemia (1); lung adenocarcinoma (1); lung carcinoma (1); mood disorder (1); ovarian carcinoma (1).